PARP2 (poly(ADP-ribose) polymerase 2)
Diseases named in the same sentence as PARP2 in open-access papers (continued):
Sharing a sentence is not in itself a finding about the gene and the disease.
Obesity (5 papers, 2011 to 2024). Accumulation of substantial excess body fat. "In contrast, miR-149-5p was downregulated in skeletal muscle upon diet-induced obesity in mice, thus contributing to reduced mitochondrial biogenesis and IR partially due to PARP-2 upregulation." (PMID 39263327, 2024). "The regulation of PPAR by PARP2 suggests the possibility of targeting PARP2 in the treatment of diseases (e.g., obesity and related metabolic disorders)." (PMID 31500199, 2019). "Furthermore, Parp2−/− mice have shown obvious protection against diet-induced obesity." (PMID 31500199, 2019). "The deletion of either the PARP-1 or PARP-2 gene in mice enhances SIRT1 activity, which leads to a higher mitochondrial content, ability to oxidize fatty acids, ultimately culminating in the prevention against diet-induced obesity." (PMID 21566260, 2011). "Via this way, PARP-2 gene deletion induced SIRT1 levels in all tissues and cell models tested, subsequently promoting mitochondrial biogenesis, enhancing the ability to oxidize fat and preventing against the onset of diet-induced obesity." (PMID 21566260, 2011).
colitis (4 papers, 2022 to 2026). Inflammation of the colon. "Colitis: PARP2 deficiency in T cells → (↓TNFα/IL‐17 + ↓oxidative stress/PARP1 activation) → suppresses intestinal inflammation." (PMID 40904702, 2025). "One available study showed that inhibition of PARP2 expression by antisense nucleotide was also found effective in ameliorating colitis in IL-10 deficient mice." (PMID 37457706, 2023). "Our results confirmed that T cell-specific PARP2 downregulation ameliorated LPS-induced colitis." (PMID 37457706, 2023). "Our results suggest that PARP2 suppression in T cells is protective in LPS-induced colitis." (PMID 37457706, 2023). "PARP1 and PARP2 have also been documented to promote colitis in mice." (PMID 35976971, 2022). "As the cellular and humoral alterations in LPS-induced colitis are similar to the changes seen in IBD, especially during the initiation of the disease and in its acute exacerbations, T cell-specific PARP2 inhibition might be beneficial in these conditions." (PMID 37457706, 2023).
Fanconi anemia (4 papers, 2015 to 2021). Fanconi anemia (FA) is a hereditary DNA repair disorder characterized by progressive pancytopenia with bone marrow failure, variable congenital malformations and predisposition to develop hematological or solid tumors. "Protein interaction analysis indicates that this “genic signature” (Dclre1a, Rev1, Xpa, Pms2, Brca2, Parp2, Smc3, Nbn, Bax) is mainly involved in the Fanconi anemia pathway and homologous recombination repair." (PMID 34573315, 2021).
glioma (4 papers, 2021 to 2023). A benign or malignant brain and spinal cord tumor that arises from glial cells (astrocytes, oligodendrocytes, ependymal cells). "DTX3L is reported to regulate the ubiquitin modification of PARP family proteins (PARP1, PARP2, PARP9, PARP14), promoting proliferation, migration and chemotherapy resistance of lymphoma, glioma, and melanoma." (PMID 38304253, 2023). "Further, the cytotoxic and DNA damage effect of the IR+PARGi combination was strongly suppressed by pre-treatment with the PARP1/PARP2 inhibitor ABT-888 (PARPi; Veliparib, 10 μM) in several GSCs as well as the model glioma cell line, LN428." (PMID 34806016, 2021).
hepatocellular carcinoma (4 papers, 2019 to 2022). A malignant tumor that arises from hepatocytes. "In conclusion, our study determined the prognostic and immunological roles of necroptosis‐related molecules such as TRAF2, PGAM5, ATG16L1, CADR9, PCYT1A, PARP2 and TLR2 in hepatocellular carcinoma." (PMID 35293027, 2022). "Hepatocellular carcinoma (HCC) has been demonstrated to have higher levels of PARP1 and PARP2 expression when compared to matched non-malignant tissue." (PMID 34440228, 2021).
lung carcinoma (4 papers, 2013 to 2022). "PARP activation occurs in the muscles of mice that develop lung cancer, and deletion of either PARP1 or PARP2 reduces body weight loss, decreases the expression of genes involved in muscle proteolysis, and promotes the expression of anabolic markers in lung cancer‐induced cachexia." (PMID 32730698, 2020). "Moreover, in the gastrocnemius muscle of lung cancer-cachectic mice, Parp-1 inhibition through miR-133a, miR-206 and miR-486 seems to promote muscle proliferation and differentiation while Parp-2 inhibition through miR-206 seems to promote muscle differentiation." (PMID 32325796, 2020). "Overall, this study suggests that Parp-1 rather than Parp-2 inhibition seems to exert more beneficial effects on muscle-related miRs expression of cachectic limb muscles in this specific mouse model of lung cancer cachexia." (PMID 32325796, 2020).
asthma (3 papers, 2014 to 2023). "The PARP2 encodes a protein from PARP enzymes, which play key roles in asthma pathogenesis by affecting the expression of pro-inflammatory genes and chemokines." (PMID 36979655, 2023). "Most cell types present in the lungs express abundant PARP-1 and PARP-2 in their nuclei and PARP inhibitors can modify their sensitivity to oxidative stress and possibly their role in asthma pathophysiology." (PMID 24444146, 2014). "PARP2 deletion does not seem to influence Th2-mediated inflammatory processes, whereas the deletion or inhibition of PARP1 was anti-inflammatory in mouse models of contact hypersensitivity reaction, asthma, acute pancreatitis, allergic airway inflammation, and experimental colitis." (PMID 37351597, 2023).
breast tumor (3 papers, 2015 to 2020). "Studies in breast tumours on associations between PARP2 protein or mRNA expression and prognosis are supportive of our data although results are not conclusive." (PMID 26674097, 2015). "Talazoparib and Olaparib are two drugs used to target PARP1 and PARP2 genes that could be mutated in advanced breast tumors." (PMID 30538267, 2018).
experimental autoimmune encephalomyelitis (3 papers, 2013 to 2025). An autoimmune demyelinating disease of the central nervous system that is produced experimentally in animals by the injection of homogenized brain or spinal cord in Freund's adjuvant. "In experimental autoimmune encephalomyelitis (EAE), a murine model of multiple sclerosis, PARP1 deletion increased, while PARP2 deletion reduced EAE-associated neuroinflammation." (PMID 37351597, 2023). "Furthermore, in experimental autoimmune encephalomyelitis, PARP2 knockout (PARP2–/–) mice demonstrate delayed disease onset and markedly reduced T helper 17 (Th17) lymphocytes, thus leading to attenuated central nervous system inflammation." (PMID 40904702, 2025).
melanoma (3 papers, 2013 to 2023). A malignant, usually aggressive tumor composed of atypical, neoplastic melanocytes. "A combined treatment of these melanoma cell cultures with Talazoparib respectively Niraparib plus IR tended to increase the PARP2 content." (PMID 34073147, 2021). "The baseline PARP1 and PARP2 levels were higher in the four melanoma cell lines ANST, ARPA, RERO and LIWE compared to the two healthy skin fibroblast cell cultures SBLF7 and SBLF9." (PMID 34073147, 2021). "We found that the protein levels of PARP1 and PARP2 were higher in the melanoma cells compared to the healthy skin fibroblasts." (PMID 34073147, 2021). "To summarize, a combined treatment of PARP inhibitor and IR primarily resulted in a decrease or a constant level of PARP1 content, whereas the PARP2 content increased in all four melanoma cell lines." (PMID 34073147, 2021). "The PARP2 expression in the untreated control groups of all four tested melanoma cell cultures indicated similar levels." (PMID 34073147, 2021). "In the control groups of the four melanoma cell lines, ANST, ARPA, RERO and LIWE, the relative levels of PARP1 appeared to be higher than those of PARP2." (PMID 34073147, 2021).
osteosarcoma (3 papers, 2020 to 2024). A usually aggressive malignant bone-forming mesenchymal neoplasm, predominantly affecting adolescents and young adults. "The role of PARP-1 in the anti-clonogenic effect is also supported by our unpublished data from experiments with PARP-1 and PARP-2 silenced osteosarcoma cells." (PMID 32392755, 2020). "Furthermore, the study demonstrates a significant negative correlation between the expression levels of poly(ADP-ribose) polymerase 2 (PARP2) and immune infiltrate in osteosarcoma samples." (PMID 39359731, 2024).
B cell lymphopenia (2 papers, 2020 to 2021). "Similarly, B cell lymphopenia in dual PARP-1/PARP-2-deficient mice can affect the recruitment of B cells to the tumor microenvironment." (PMID 32046278, 2020). "The role of PARP2 in thymocyte development and B-cell lymphopenia are some of the well-studied processes." (PMID 34445986, 2021).
bone marrow failure (2 papers, 2023 to 2024). "PARP-2-deficient mice were associated with an increase in HSPC death, and in response to radiation, PARP-2 deficiency, and not PARP-1 deficiency, resulted in bone marrow failure." (PMID 39201718, 2024).
cardiac hypertrophy (2 papers, 2023 to 2024). "PARP2 has been associated with cardiac hypertrophy, TEP1 has been associated with myocardial infarction (MI) and ischemic stroke, and TTC5 has been associated with cardiovascular disease." (PMID 38473795, 2024). "The gene PARP2, poly(ADP-ribose) polymerase 2, has been associated with cardiac hypertrophy in both mouse and human research studies." (PMID 38473795, 2024). "The poly (ADP-ribose) polymerases (PARPs) family members such as PARP-1 and PARP-2 has been revealed to participate in the progression of cardiac hypertrophy due to different cellular localization and regulating mechanisms." (PMID 37219631, 2023). "PARP-1 contributes to caspase-independent myocyte cell death during heart failure while knockdown of PARP-2 protects against cardiac hypertrophy via SIRT1 activation." (PMID 37219631, 2023).
colon cancer (2 papers, 2019 to 2021). "PARP1 and PARP2 were both activated in MSI subtype colon cancer patients’ tissue and cell lines." (PMID 31221124, 2019).
dermatitis (2 papers, 2023 to 2025). An inflammatory process affecting the skin. "To characterize the functional significance of PARP2 expression in psoriasis, we applied an acknowledged murine model of psoriasis, using imiquimod (IMQ)-induced dermatitis on PARP2−/− and littermate PARP2+/+ male mice." (PMID 37351597, 2023). "We observed that the deletion of PARP2 attenuated the imiquimod-induced psoriasis-like dermatitis in mice." (PMID 37351597, 2023). "Psoriasis: PARP2 silencing → ↑estradiol → inhibits NF‐κB → alleviates dermatitis." (PMID 40904702, 2025). "In sharp contrast, we previously reported exacerbation of the Th17-mediated IMQ-induced psoriasis-like dermatitis in PARP1−/− mice, while the present study shows the beneficial effect of PARP2 deletion in the IMQ model." (PMID 37351597, 2023). "We performed the IMQ-induced dermatitis as follows: PARP2+/+ and PARP2−/− mice that were treated with vehicle and IMQ (WP and PP mice, respectively), and PARP2+/+ and PARP2−/− mice that were treated with topical exemestane solution prior to treatment with IMQ (WPE and PPE mice, respectively)." (PMID 37351597, 2023).
liver cancer (2 papers, 2014 to 2022). An epithelial or non-epithelial malignant neoplasm that arises from the liver. "PARP-1 and PARP-2 mRNA expression appear to be up-regulated in most of the liver cancer cell lines studied in comparison with PHHs although not all the differences in expression were significant." (PMID 25139788, 2014).
neuroblastoma (2 papers, 2020 to 2021). Neuroblastoma (NB) is the most common solid, extracranial childhood tumor. "We also tested the association between PARP1 and PARP2 expression with clinical outcome by quantitative real‐time PCR (RT‐qPCR) analysis of 20 mRNA samples extracted from stage 4 neuroblastomas." (PMID 32103589, 2020). "High CHK1 mRNA expression is associated with a reduced survival in neuroblastoma patients, independently from MNA, with the same trend we previously reported for PARP1 and PARP2." (PMID 34508175, 2021).
psoriasis (2 papers, 2023 to 2025). An autoimmune condition characterized by red, well-delineated plaques with silvery scales that are usually on the extensor surfaces and scalp. "In human keratinocytes, PARP2 silencing suppressed hyperproliferation, preserved terminal differentiation markers, and reduced inflammatory mediator production after stimulation with psoriasis‐associated cytokines (IL‐17A and TNFα)." (PMID 40904702, 2025). "Exemestane abolished the anti-inflammatory effect of PARP2 deletion in the IMQ model as determined by the concentration of several psoriasis-related cytokines measured in the skin of mice." (PMID 37351597, 2023). "In this study, we assessed the role of PARP2 in a Th17-mediated inflammatory skin condition, psoriasis." (PMID 37351597, 2023). "The known similarities and differences in the functions of PARP1 and PARP2 prompted us to assess the role of PARP2 in psoriasis." (PMID 37351597, 2023). "We assessed the expression of PARP2 in lesional skin biopsies of psoriasis patients and in normal skin from similar regions of healthy subjects." (PMID 37351597, 2023). "With our results, we propose the stimulation of keratinocytes’ innate estrogen production by targeting PARP2 as a potential approach in psoriasis management." (PMID 37351597, 2023). "Apparently, PARP2-depleted human keratinocytes phenocopied the role of PARP2 in human psoriatic skin and in a murine psoriasis model, which called for further investigations into the role of PARP2 in inflammatory regulation in keratinocytes." (PMID 37351597, 2023). "Therefore, we studied the functional consequence of decreased PARP2 expression in murine and cellular human models of psoriasis." (PMID 37351597, 2023). "Silencing of PARP2 in human keratinocytes prevented their hyperproliferation, maintained their terminal differentiation, and reduced their production of inflammatory mediators after treatment with psoriasis-mimicking cytokines IL17A and TNFα." (PMID 37351597, 2023). "In summary, we highlighted a yet unknown mechanism by which PARP2 may be involved in inflammatory regulation and identified a potential targetable player in psoriasis." (PMID 37351597, 2023). "Based on our findings, we hypothesize that during the progression of psoriasis, Th1 and Th17-derived cytokines (such as TNFα and IL17A) may induce PARP2 in keratinocytes, which may turn down aromatase activity and estrogen synthesis in keratinocytes that may trigger NF-κB activation." (PMID 37351597, 2023). "Given that the protective effect of genetic deletion or depletion of PARP2 in psoriasiform inflammation may probably be boiled down to increased estradiol synthesis of keratinocytes, our data might raise the potential of repurposing PARP inhibitors in the treatment of psoriasis." (PMID 37351597, 2023).
rheumatoid arthritis (2 papers, 2019 to 2021). A chronic, systemic autoimmune disorder characterized by inflammation in the synovial membranes and articular surfaces. "PARP2 (ARTD2) expression in synovial cells from a rat rheumatoid arthritis model was found to be increased compared to control cells." (PMID 34725336, 2021).
Thrombocytopenia (2 papers, 2015 to 2022). A reduction in the number of circulating thrombocytes. "MK-4827 (niraparib), an orally available compound, demonstrating strong PARP-1 and PARP-2 inhibitory activity has the side effects of nausea, vomiting, fatigue and thrombocytopenia." (PMID 25606064, 2015).
triple-negative breast carcinoma (2 papers, 2013 to 2022). An invasive breast carcinoma which is negative for expression of estrogen receptor (ER), progesterone receptor (PR), and human epidermal growth factor receptor 2 (HER2). "For degradation of PARP2, Olaparib was successfully conjugated to KB02 via a PEG linker and showed degradation of PARP2 in triple-negative breast cancer (TNBC) cell lines MDA-MB-231 both in vitro and in vivo." (PMID 36500212, 2022).
viral infection (2 papers, 2017 to 2026). "For PARP2, this extends beyond IAV infection as we have found that the same sQTL locus colocalized with anti-HSV-1 IgG, indicating that these two PARP2 isoforms have broader roles during viral infection that will be investigated mechanistically in future work." (PMID 41542048, 2026). "In addition to T-cell lymphopenia affecting both the CD4+ and CD8+ compartment, virus infection also revealed a redundant role of PARP-1 and PARP-2 in T-cell effector function." (PMID 28181505, 2017).
acute myelogenous leukemia (1 paper, 2020). "Our research suggests that there is a different regulation of PARP1, PARP2, PARP3, and TRPM2 gene expression in acute myelogenous leukemia cells." (PMID 32423430, 2020). "The results found that the bone marrow cells of the patients with acute myeloid leukemia (AML) show overexpression of PARP1 and PARP2 genes and decreased TRPM2 gene expression." (PMID 32423430, 2020). "Our research suggests that there is a different regulation of PARP1, PARP2, PARP3, and TRPM2 genes expression in acute myelogenous leukemia cells." (PMID 32423430, 2020). "In acute myelogenous leukemia cells, PARP1, PARP2, and TRPM2 gene mRNA levels deregulate." (PMID 32423430, 2020). "In our studies we showed that in the bone marrow cells of patients with acute myeloid leukemia, PARP1 and PARP2 genes are overexpressed and TRPM2 gene is down-regulated, which may suggest disturbed signaling between these genes." (PMID 32423430, 2020). "Interestingly, the bone marrow cells of patients with acute myelogenous leukemia show over expression of PARP1 and PARP2 genes and decreased TRPM2 gene expression." (PMID 32423430, 2020). "PARP1, PARP2, and TRPM2 genes at mRNA level deregulate in acute myeloid leukemia cells." (PMID 32423430, 2020).
chronic obstructive pulmonary disease (1 paper, 2020). A chronic and progressive lung disorder characterized by the loss of elasticity of the bronchial tree and the air sacs, destruction of the air sacs wall, thickening of the bronchial wall, and mucous accumulation in the bronchial tree. "We aimed to assess PARP-1 and PARP-2 expression and activity and DNA damage in tumors and non-tumor lungs from patients with/without chronic obstructive pulmonary disease (COPD)." (PMID 33187221, 2020).
colorectal tumors (1 paper, 2025). "In conclusion, MSI colorectal tumors exhibited TYMS and PARP2 upregulation and DFFA downregulation." (PMID 41440189, 2025).
esophageal cancer (1 paper, 2024). A primary or metastatic malignant neoplasm involving the esophagus. "In specifically, circ-RAD23B regulates PARP2 and AKT2 by sponging miR-5095 in esophageal cancer." (PMID 38289973, 2024).
Ewing sarcoma (1 paper, 2016). A small round cell tumor that lacks morphologic, immunohistochemical, and electron microscopic evidence of neuroectodermal differentiation. "In addition, mutations in PARP-1 and PARP-2 are seldom observed in Ewing sarcoma." (PMID 27635231, 2016). "In addition to catalytic inhibition, PARP inhibitors exert their cytotoxicity by tightly trapping PARP-1 and PARP-2 to DNA at sites of single-strand breaks, andin vitro Ewing sarcoma inhibitor sensitivity correlates with PARP trapping potential." (PMID 27635231, 2016).
glioblastoma (1 paper, 2025). The most malignant astrocytic tumor (WHO grade IV). "Our results showed decreased gene expression of PARP1 and PARP2 in MDR glioblastoma cells, while MDR NSCLCs exhibited increased mRNA expression of these genes." (PMID 40006556, 2025).
haemolytic anaemia (1 paper, 2022). "Preclinical evidence suggests that PARP-2 plays a pivotal role in erythroid differentiation and its deletion leads to extravascular haemolytic anaemia suggesting that PARP inhibitors may impact haematopoiesis, which may explain the haematological AEs observed in these studies." (PMID 35598359, 2022).
HCMV infection (1 paper, 2022). "Thus, whether PARP-2 is also involved in the HCMV infection process still needs further studies." (PMID 36146855, 2022).